CD4 (CD4 molecule)
Diseases named in the same sentence as CD4 in open-access papers (continued):
Sharing a sentence is not in itself a finding about the gene and the disease.
rectum adenocarcinoma (17 papers, 2019 to 2025). An adenocarcinoma arising from the rectum. "Notably, high miR-425 and miR-576 expression shortened the overall survival time of rectum adenocarcinoma (READ) patients with either CD4+ or stage II, which both were closely related to CRC metastasis." (PMID 34490081, 2021). "For colon and rectum adenocarcinoma, we find higher levels of CD4, CD8A, and PD-1 in cytomegalovirus-positive tumors than in virus-negative tumors, though other T-cell genes only showed modest differential expression in cytomegalovirus-positive and virus-negative tumors." (PMID 30911684, 2019). "= 0.213, p=0.0119) in rectum adenocarcinoma (READ), while METTL14 expression was not significantly correlated with CD4+ T cell infiltration (cor." (PMID 34221955, 2021).
renal dysfunction (17 papers, 2010 to 2025). "Other factors associated with renal dysfunction include, being older, being female, African-American ethnicity, low weight, low CD4 count, high viral load and having co-morbid conditions." (PMID 32571236, 2020). "Among them, baseline CD4 count, baseline eGFR, baseline proteinuria, history of cancer, and cotrimoxazole prophylaxis therapy were significantly associated with renal dysfunction." (PMID 30863641, 2019). "Only age greater than 50 years, baseline CD4 count less than 200 cells/mm3, and baseline proteinuria were significantly associated with renal dysfunction in multivariable logistic regression." (PMID 30863641, 2019). "In the present study, renal dysfunction was detected in 16 (25.4%) of study participants and factors associated with renal dysfunction were age greater than 50 years, baseline CD4 count less than 200 cells/mm3, and baseline proteinuria." (PMID 30863641, 2019). "Age greater than 50 years, CD4 count less than 200 cells/mm3, and baseline proteinuria were risk factors for the occurrence of renal dysfunction." (PMID 30863641, 2019). "A proportion of patients treated with ABC had low CD4 count and others were hypertensive, both conditions are known risk factors for renal dysfunction." (PMID 22242194, 2012). "A small body weight is considered a risk factor for TDF-associated renal dysfunction, in addition to old age, high baseline serum creatinine level, low CD4 count, concurrent use of ritonavir-boosted protease inhibitor, and concurrent use of nephrotoxic drugs." (PMID 21799928, 2011). "Known risk factors for the development of TDF-induced nephrotoxicity include underlying renal dysfunction, low CD4 count and low body weight, concomitant use of boosted PI and other nephrotoxic agents." (PMID 21808434, 2010). "In another study, including HIV patients with TB, a low CD4 (cluster of differentiation 4) cell count (<200/μL), renal dysfunction, diffuse parenchymal disease, miliary pattern, and untreated TB were associated with increased mortality." (PMID 35449613, 2022). "A similar cohort of HIV-infected persons in Tanzania found predictors of renal dysfunction in multivariate analysis include female, BMI, CD4 cell count <200 cells/mm3 and WHO clinical stage II or above." (PMID 36108078, 2022). "The Zambian study reported by Watankisha found a high burden of renal dysfunction in older patients with low CD4 counts reporting point prevalence of kidney dysfunction among these patients as 18.6% at 18 months follow up." (PMID 31171021, 2019). "An association has been reported between low CD4 count and renal dysfunction after ART initiation, from programmatic studies, with median baseline CD4 counts ranging from 154 to 209 cells/μL." (PMID 30963667, 2019). "Individuals excluded because of missing baseline eGFR were more likely to have higher baseline CD4 counts and inclusion of these individuals in the study sample could have resulted in lower rates of renal dysfunction being reported." (PMID 30963667, 2019). "This is one of the first studies to evaluate the association between baseline CD4 count and renal dysfunction in the context of routine provision of ART regardless of CD4 count in a high‐burden programmatic setting." (PMID 30963667, 2019). "Also similar to previous studies 13, 16, 28, this study showed lower baseline prevalence of renal dysfunction at baseline CD4 counts > 200 cells/μL and among younger individuals." (PMID 30963667, 2019). "This study showed low rates of renal dysfunction at baseline and on ART, with lower rates of baseline renal dysfunction among individuals with baseline CD4 counts > 200 cells/μL." (PMID 30963667, 2019). "This case emphasizes the importance of maintaining a high index of suspicion for HIVAN in all patients infected with HIV who are experiencing renal dysfunction and proteinuria, regardless of racial background, CD4 count, or viral load." (PMID 40718301, 2025).
Shock (17 papers, 2009 to 2026). The state in which profound and widespread reduction of effective tissue perfusion leads first to reversible, and then if prolonged, to irreversible cellular injury. "Particularly, PDL2 expression is increased in circulating monocytes and CD4+ T lymphocytes in patients with septic shock." (PMID 32849606, 2020). "in their study of 64 patients with septic shock reported increased expression of PD-1 and its ligands on the MO and CD4+T lymphocytes on days 1–2 and 3–5 after the onset of septic shock." (PMID 29049359, 2017). "In critically ill patients with septic shock, an increase in PD-1+CD4+ lymphocytes when compared with healthy volunteers has also been observed." (PMID 24289156, 2013). "In patients with septic shock, the subpopulation with active caspase-3 was elevated in CD4+ T cells, CD8+ T cells and CD19+ B cells compared with healthy controls." (PMID 21349174, 2011). "The combined high-risk category (CD4 < 50 cells/μL and TyG ≥ 9.22) displayed the most severe phenotype, with lower platelet, monocyte, and albumin levels; higher LDH, CRP, and bilirubin concentrations; a mean SOFA score of 6.1; and the highest incidence of septic shock (41.6%)." (PMID 41601726, 2026). "In this study, we observed a dramatic decrease in the lymphocyte, T cell, CD4+ T cell, CD8+ T cell, B cell, and NK cell counts of patients with septic shock." (PMID 36845110, 2023). "We observed that the percentage of IL-2–producing cells was significantly decreased among CD4+ T cells at D1 and D3 and among CD8+ T cells at D1 in patients with septic shock in comparison with HVs." (PMID 30995946, 2019). "Thus, it is possible to suggest that the expansion of CD4+CD45RA-CD45RO+ T lymphocytes observed here during the follow up of surviving patients might be considered a compensatory anti-inflammatory mechanism that develops in these patients with septic shock." (PMID 19243622, 2009). "Moreover, we observed a significant inverse correlation between increased PD-1 and PD-L1 CD4+ lymphocyte expressions and decreased PHA-induced lymphocyte proliferation in patients with septic shock." (PMID 21418617, 2011).
silicosis (17 papers, 2006 to 2025). Silicosis is a respiratory disease caused by breathing in (inhaling) silica dust. "Significantly, targeting the maintenance and function of pathogenic lung CD4+ TRM cells exerted protective effects against silicosis." (PMID 39122899, 2024). "Collectively, these data demonstrated CS stimulated the emergence and expansion of pulmonary CD4+ TRM cells that were tightly related to silicosis progression." (PMID 39122899, 2024). "Particularly, the treatments at different time points within silicosis progression were employed to elucidate the origin and maintenance of CD4+ TRM cells." (PMID 39122899, 2024). "With the expansion of CD4+ TRM cells, there was an increasing number of CD69+CD103+ and CD69+CD103– subsets, implying their pathogenic roles in silicosis." (PMID 39122899, 2024). "Here we showed that a substantial accumulation of pulmonary CD4+ TRM cells mediated the pathogenesis of silicosis, which exerted immunological memory and antigen-specific response to the invaded CS particles." (PMID 39122899, 2024). "Considering persistent particle exposure in the working environments, we adopted a repeated CS exposure model, exploring the role of CD4+ TRM cells in mediating silicosis." (PMID 39122899, 2024). "To this end, we utilized a murine model of silicosis delineating the effects of CS particles on CD4+ TRM cells and further explored its pathogenic role in silicosis." (PMID 39122899, 2024). "Remarkably, the ratio of CD103+ to CD103– in CD69+CD4+ TRM cells was lifted with silicosis progression, emphasizing the immune imbalance within TRM subsets would be related to fibrogenesis." (PMID 39122899, 2024). "In synthesis, these results demonstrated that CD4+ TRM cells exerted immuno-memory to the CS particles mediated the pathogenesis of silicosis, and the CD69+CD103– TRM subsets possessed robust pathogenic capacity to silicosis." (PMID 39122899, 2024). "The percentage of naïve Th cells (CD3+CD4+CD45RA+CD45RO−) was significantly lower in the samples from patients with silicosis in both the SS and PMF groups than in those from the HC group." (PMID 38891910, 2024). "PD-1 expression was significantly upregulated in CD4+ T cells in lung tissues of mice with early and late silicosis, while it was downregulated in CD8+T cells in lung tissues of mice with early silicosis." (PMID 37275876, 2023). "This study found that the peripheral blood lymphocytes of patients with silicosis highly expressed PD-1, and the immune depletion of CD4+T cells and NK cells was the main reason for the higher false negative rate of QFT." (PMID 36587204, 2022). "Significantly lower PD-1 expression was detected on CD4+ T cells in PB from the asbestosis (mean 7.753%) and silicosis (mean 6.676%) groups than in PB from the healthy control group (mean 11.790%, P < 0.01)." (PMID 34022844, 2021). "CD4+CD25+ Treg was claimed to have a crucial role in regulating silicosis development and the crystalline silica-induced Th immune response according to our previous study." (PMID 28831210, 2017). "Our previous studies demonstrated that CD4+ T helper (Th) cells played a crucial role in immune response in silicosis." (PMID 28831210, 2017). "Our previous studies also delineated that different subsets of CD4+ T cells regulated the pathology of silicosis arranging from inflammation stage to fibrosis stage." (PMID 27069316, 2016). "The percentage of peripheral blood CD4+CD25+ Foxp3+ Treg cells is slightly lower in silicosis patients (SILs) compared with healthy donors (HD) and the function of Treg cells in SILs is less significant than in HDs." (PMID 21072213, 2010). "Treg cells are identified in the development of silicosis; however, the mechanism of CD4+CD25+Foxp3+ Treg cells to regulate immune homeostasis is still poorly understood in silicosis." (PMID 21072213, 2010).
silicosis (continued). "Hubbard reported no decrease in silicosis in T-cell deficient "nude" (Balb/cnu/nu) mice, while Barbarin and colleagues observed decreased silicosis in mice treated with anti-CD4 antibody." (PMID 16396683, 2006). "Given the situation of repeated CS stimulation and the immunologic memory function of TRM cells, we hypothesized that CD4+ TRM cells are involved in the pathogenesis of silicosis." (PMID 39122899, 2024). "However, the percentage of memory Th cells (CD3+CD4+CD45RA−CD45RO+) was significantly increased in the silicosis groups compared to the HC group." (PMID 38891910, 2024). "We further proved the source and function of CD4+ TRM cells in the pathogenesis of silicosis." (PMID 39122899, 2024). "In the current study, we documented significantly decreased PD-1 expression on CD4+ T or CD8+ T cells in PB from patients with asbestosis and silicosis, and the proportions of CD4+/CD8+ PD-1+ T cells were positively correlated with the percentage of FVC predicted in patients with asbestosis." (PMID 34022844, 2021). "However, PD-L1 expression on circulating CD4+ T cells was significantly decreased in the asbestosis (mean 0.212%) and silicosis (mean 0.310%) groups compared to the healthy control group (mean 0.705%) (P < 0.05)." (PMID 34022844, 2021). "It has been well established that CD4+ T cells played an important role in silicosis." (PMID 27069316, 2016). "Many studies have proved that CD4+ T lymphocytes participated in the pathogenesis of silicosis." (PMID 27069316, 2016). "However, the actual role of B10 on CD4+ T cells in silicosis still needs further exploration." (PMID 28831210, 2017). "However, exposure to silica induced the apoptosis of CD4+ T cells; gene silencing of β-catenin during silicosis may extinguish the antiapoptotic property contributed by Wnt pathway." (PMID 27069316, 2016). "Here we show that pulmonary CD4+ tissue-resident memory T cells (TRM) accumulate in response to CS particles, mediating the pathogenesis of silicosis." (PMID 39122899, 2024). "In previous studies, infiltration by CD4 + T cells and CD8 + T cells have been observed in silicosis." (PMID 36615800, 2022). "Further analysis found that the ratio of PD-1+CD4+T and IFN-γwere negatively correlated and blockaded the PD-1 pathway with antibodies can restore the sensitivity of QFT-GIT in silicosis." (PMID 36587204, 2022). "PD-1 was expressed at significantly lower levels on CD4+ or CD8+ peripheral T cells from patients with asbestosis and silicosis than on cells from healthy controls." (PMID 34022844, 2021). "CD4+CD25− effector T cells (Teff), such as Th1, Th2, and Th17, took part in different stages of silicosis according to the murine studies." (PMID 28831210, 2017). "Therefore, to emphasize the relationship between these two subpopulations, the CD4+/CD8+ T cells’ ratio was calculated, and this ratio was significantly lower in both silicosis patient groups than in the HC group." (PMID 38891910, 2024). "In synopsis, we proved the cell retention markers CD103 and CD69 can define CD4+ TRM cells into functional distinct lineages, which may provide potential therapeutic targets for alleviating silicosis." (PMID 39122899, 2024). "The expression of PD-1 in CD4+ T cells was significantly increased in lung tissues of early and late silicosis, but there was no significant change in peripheral blood." (PMID 37275876, 2023). "Furthermore, lymphocytes (predominantly CD4+ T cells, but also numerous CD8+ T cells and natural killer cells) are known to be abundant in the lesions of silicosis." (PMID 28360865, 2017). "Thus, modulating immuno-balance within CD4+ TRM cells that restrained the number and function of CD69+CD103− TRM subsets may provide therapeutic effects in treating silicosis." (PMID 39122899, 2024).
silicosis (continued). "The expression of PD-1 on CD4+ and CD8+ T cells and the expression of PD-L1 and PD-L2 on CD14+ monocytes in peripheral blood of silicosis patients are significantly lower than those of healthy people, and the downregulation of PD-1 may be related to the single nucleotide polymorphism of PDCD1 gene." (PMID 37275876, 2023). "Additionally, proliferation of helper T (CD3+ CD4+) and cytotoxic T (CD3+ CD8+) cells exposed to 10 μg/ml Ludox or NM-200 was significantly higher in silicosis patients than in controls, although SI values >2.5 were only observed in CD3+ CD8+ cells when exposed to 10 μg/ml Ludox." (PMID 36311760, 2022). "The CS-stimulated pulmonary CD4+ TRM cells expressed CD69, regardless of Teff cells or Tregs, implying a crucial role of this molecule in silicosis." (PMID 39122899, 2024). "No significant change in the percentages of CD3+ CD4+ and CD3+ CD8+ subpopulations was observed between silicosis patients and controls, per concentration of both Ludox and NM-200." (PMID 36311760, 2022). "Unlike the circulating CD4+ TEM cells (CD44+CD45 i.v.+), CD4+ TRM cells surged continuously with the progression of silicosis, suggesting a link between the emergence of CD4+ TRM cells and silicosis progression." (PMID 39122899, 2024). "Our results are consistent with findings observed in several studies with patients with silicosis and partially fit with the results presented by others in which only a reduction in CD4+ T cells but no changes in CD8+ T cells or in the CD4+/CD8+ T cell ratio were observed." (PMID 38891910, 2024).